PIK3CA (phosphatidylinositol-4,5-bisphosphate 3-kinase catalytic subunit alpha)
Diseases named in the same sentence as PIK3CA in open-access papers (continued):
Sharing a sentence is not in itself a finding about the gene and the disease.
breast cancer (continued). "For example, PTEN-deficient breast cancer cells are resistant to the pan-PI3K inhibitor GDC-0941 and PI3K/mTOR dual inhibitor BEZ-235, unlike those harboring mutations in PIK3CA and HER219–21." (PMID 33431808, 2021). "It was stated that the average expression level of the PIK3CA, PIK3R1, PTEN genes in the group of breast cancer patients is lower in comparison to the control group, while the average expression level of the AKT1 and mTOR genes in the studied group was higher in comparison to the control group." (PMID 33669698, 2021). "Another study demonstrates that the presence of PIK3CA/AKT1 mutations and absence of alterations in MTOR or TSC1 were associated with sensitivity to capivasertib monotherapy in HER2− breast cancer." (PMID 34419139, 2021). "Activation of PIK3CA mutations and deletion of PTEN (PTEN is a key negative regulator of PI3K signaling) lead to resistance to trastuzumab and lapatinib in breast cancer cell lines, and low PTEN levels are associated with worse patient prognosis." (PMID 34778044, 2021). "In the METABRIC breast cancer dataset, no significant OS difference was observed between the PIK3CA-mutant and wild-type groups." (PMID 34093841, 2021). "Thus, these cells will permit a comprehensive approach to evaluating potential drugs targeting PIK3CA/PTEN–wild‐type, HER2‐positive, trastuzumab‐resistant breast cancer, which comprises a large proportion of the trastuzumab‐resistant breast cancer population." (PMID 33665980, 2021). "A pooled analysis showed that the presence of PIK3CA mutations is a negative prognostic factor (pooled overall survival [OS], disease‐free survival [DFS], and progression‐free survival [PFS]) in breast cancer." (PMID 32697890, 2020). "The causes and clinical significance of the relationship between PIK3CA mutations and low APOBEC expression in breast cancers are not yet clear." (PMID 32176735, 2020). "Furthermore, a systematic understanding is lacking regarding the prevalence of PIK3CA mutations in HR+/HER2- advanced/unresectable or metastatic breast cancer or within clinically relevant molecular BC subgroups." (PMID 32637176, 2020). "This recently resulted in the approval of Alpelisib/BYL719 for advanced PIK3CA mutation positive, hormone receptor positive, HER2 negative breast cancer patients." (PMID 33051521, 2020). "Although, PIK3CA is not found in treatment guidelines for breast cancer, as is the case for ERBB2, ESR1 or PGR, it is an oncogene found downstream ERBB2." (PMID 31169290, 2019). "For example, 53.0% of IDCs contained clonal subpopulations expected to be PIK3CA and MAP kinase pathway mutant, suggesting that combinations of molecularly-targeted therapies may be required for adequate treatment of breast cancer." (PMID 30813596, 2019). "Of note, breast cancer cell lines with PTEN loss (CAMA-1, BT-549 and ZR-75-1) were not sensitive to RNMT inhibition, suggesting that PIK3CA mutations, rather than PTEN loss, promotes RNMT dependency in breast cancer." (PMID 30991934, 2019). "Also in the breast cancer field, in a phase III clinical trial of breast cancer treatment with CDK4/6 inhibitors, the detection of changes in ctDNA PIK3CA levels after 15 days of treatment predicts progression-free survival (PFS) after treatment." (PMID 30849971, 2019).
breast cancer (continued). "In conclusion, the results of the current study showed higher significantly increased PIK3CA mRNA expression in breast tumor tissue compared to normal breast tissue, and contrary to expected, we also observed increased PTEN expression in breast carcinoma tissue compared to normal breast tissue." (PMID 31554385, 2019). "The expressions of PIK3CA and PTEN showed not significant relation with any clinicopathological characteristics of breast cancer, and reported not found correlation between PIK3CA and PTEN expressions." (PMID 31554385, 2019). "The present study aimed to assess the mRNA expression of PIK3CA and PTEN genes in the breast carcinoma tissue compared to their expression in the normal breast tissue, and evaluated the correlation of their expression with clinicopathological parameters in patients with BC." (PMID 31554385, 2019). "For example, a known network-based approaches such as xSeq did not report PIK3CA as a top candidate driver gene in breast cancer." (PMID 29738578, 2018). "Additional molecular alterations such as somatic PIK3CA mutations, part of the PI3K/AKT/mTOR pathway, are commonly identified in breast cancers but are not yet used in the selection of approved therapies." (PMID 29177603, 2018). "For the UBC-TAM Series univariate analysis, favorable prognostic associations for breast-cancer-specific survival (BCSS) were detected for non-silent mutations in MAP3K1, ERBB3, XBP1, and PIK3CA." (PMID 30181556, 2018). "Even though the model includes several of the pathways and signaling proteins important in ER+, HER2+, and PIK3CA-mutant breast cancer, it is not complete." (PMID 29623959, 2017). "We confirmed potent inhibition of several off-targets and were keen on reducing the inhibition of FRAP1(mTOR), PIK3CA, and CDK7, as these kinases drive proliferation in breast cancer, which would complicate the interpretation of MELK-dependent pharmacology if inhibited." (PMID 28926338, 2017). "The recent emergence of serum and glucocorticoid-regulated kinase (SGK3) as an oncogenic effector in PIK3CA-mutant breast cancer cells independent of AKT has led to the examination of INPP4B as a mediator of PI3K/SGK3 signalling." (PMID 28082369, 2017). "Epidemiologic studies suggested that mutations of the PI3K/PTEN/AKT pathway genes are associated with cancer risk, yet no data are available for PTEN rs701848, PIK3CA rs2699887, and AKT1 rs2494752 polymorphism and breast cancer(BC) risk." (PMID 28423632, 2017). "Comparatively little is known about PIK3CA gene copy number alterations and clinical outcomes in breast cancer, irrespective of ERBB2 status." (PMID 27576528, 2016). "Some contradictories are discovered to be mainly relative to the order of KRAS and PIK3CA alteration, that is, whether PIK3CA alteration as a part of RAS pathway is the late event after KRAS alteration or PIK3CA the late event in breast cancer." (PMID 27190992, 2016). "Together, these findings characterize LINC00520 as a lncRNA that is regulated by oncogenic Src, PIK3CA and STAT3, and which may contribute to the molecular etiology of breast cancer." (PMID 27626181, 2016).
breast cancer (continued). "In both datasets, changes in percentage of Ki67 decrease were not statistically different between PIK3CA mutant and wild-type breast cancer." (PMID 25857348, 2015). "It would be interesting to investigate whether RASSF2 hypermethylation is related to alterations in the PIK3CA pathway, since PIK3CA and RAS are pathways with apparently mutually exclusive alterations in breast cancer." (PMID 26284587, 2015). "Two patients (breast cancer, n = 1; NSCLC, n = 1) had a PIK3CA H1047R mutation their FFPE tumor samples, but not in cfDNA." (PMID 25980577, 2015). "Subsequently we conducted subgroup analysis in 152 ER positive breast cancers and found that there was a statistically significant difference in 5-year DFS between ER positive PIK3CA mutant and PIK3CA wild-type patients (54.2% vs. 76.2%; P = 0.011; HR = 2.383; 95%CI, 1.199–4.738)." (PMID 25816324, 2015). "In patients who did not receive tamoxifen, we did not observe an association between either PIK3CA mutation status, HER2, IGF-1R expression, or PTEN status and breast cancer prognosis." (PMID 24467828, 2014). "Activating PIK3CA mutations were present in the two breast cancer cell lines where NRG-1β did not inhibit T-DM1 activity, while the four cell lines where T-DM1 activity was reduced did not harbor PIK3CA mutations." (PMID 24887180, 2014). "PIK3CA, AKT1, PTEN and Ki67 status across a collection of 77 matched ER+ breast cancers." (PMID 24520381, 2014). "The frequencies of PIK3CA, PIK3R1 and AKT1 alteration differ according to breast cancer subtypes." (PMID 24229379, 2013). "PIK3CA expression did not vary significantly between the four breast cancer subgroups based on hormone and ERBB2 receptor status." (PMID 24229379, 2013). "In conclusion, PIK3CA mutation occurs more frequently in elder patients and the ratio of mutations in hot spots to non-hot spots is about 2.5 to 1 in HER2-positive breast cancer patients." (PMID 21676217, 2011). "OncoCarta analysis identified mutations in the brain metastases from primary breast cancers (non-autopsy cases) in NRAS (2/12 - 17%), and PIK3CA (2/12 - 17%)." (PMID 20604919, 2010). "Just as not all recurrent TNBC and HER2-rich breast cancer must undergo mastectomy, for luminal type cases, HER2 or PIK3CA mutations may be present." (PMID 41463257, 2025). "For example, the Therascreen® PIK3CA RGQ PCR kit, which received FDA approval for advanced‐stage HR‐positive/HER2 ‐negative breast cancer based on the findings of the phase III SOLAR‐1 trial, is a real‐time PCR test that screens for 11 therapy‐relevant PIK3CA mutations from plasma." (PMID 38867388, 2025). "Except PIK3CA, none of these impacting genes were breast cancer actionable." (PMID 39844043, 2025). "Expert Panel Recommendations: Based on the CAPItello‐291 study, capivasertib combined with fulvestrant is recommended for patients with locally advanced or metastatic HR‐positive/HER2‐negative breast cancer who exhibit any gene alterations in PIK3CA, AKT1, or PTEN." (PMID 40206206, 2025). "However, no PIK3CA mutations were detected in invasive lobular carcinoma cases, and HER2+ breast cancer showed the lowest mutation rate, potentially due to sample size and ethnic differences." (PMID 40472482, 2025). "While GATA3, ESR1, PIK3CA, FOXA1, FOXO3, and RB1 protein abundances were not significantly reduced in GATA3mut breast cancers, the expression of genes associated with MDM2 function and phosphorylation of genes associated with ERK signaling and aggressive phenotypes were impacted." (PMID 40439821, 2025).
breast cancer (continued). "These genes may accumulate somatic mutations in conjunction with mutations and/or amplifications of PIK3CA and AKT3, as well as deletions or mutations of PTEN, TSC1, and INPP4B in the PI3K/mTOR pathway, although not in the majority of breast cancers (BCs)." (PMID 38987766, 2024). "Additionally, novel therapeutic agents targeting frequently mutated genes like PIK3CA or BRCA1/2 have been developed and approved for treating patients with human epidermal growth factor 2 (HER2)‐negative breast cancer." (PMID 38895905, 2024). "Based on the results of the SOLAR-1 trial, alpelisib has been approved in combination with the fulvestrant for the treatment of PIK3CA-mutated, HR(hormone receptor)-positive, HER2(human epidermal growth factor receptor 2)-negative advanced breast cancer who had received endocrine therapy previously." (PMID 39070139, 2024). "Moreover, the intricate interplay between PIK3CA and the tumor microenvironment within TNBC remains a focal point of the investigation, revealing the gene's multifaceted role in shaping the complex biology of this breast cancer subtype." (PMID 39369580, 2024). "Compared with those in the Y-27632 inhibitor group, the P-JAK2 and P-PIK3CA protein levels were significantly increased after the addition of GluOC, and the results showed that ROCK1 regulated JAK2 and PIK3CA, thereby affecting the proliferation and apoptosis of MDA-MB-231 breast cancer cells." (PMID 39054484, 2024). "However, NGS identified a substantial proportion of breast cancer patients carrying potentially oncogenic or oncogenic PIK3CA mutants that are not included in the therascreen® panel." (PMID 38895905, 2024). "Similarly, the CAPItello‐291 trial evaluated the efficacy of fulvestrant, with or without capivasertib, in HR‐positive, HER2‐negative breast cancer patients who had altered AKT pathways (nearly 75% were PIK3CA‐mutant)." (PMID 38037839, 2023). "In hormone receptor–positive (HR+), human epidermal growth factor receptor 2−negative (HER2–) advanced breast cancer (ABC), phosphatidylinositol-4,5-bisphosphate 3-kinase catalytic subunit alpha (PIK3CA) is the most frequently mutated gene associated with poor prognosis." (PMID 37655108, 2023). "If postmenopausal patients with high Ki-67 luminal breast cancer plan NAC especially in expectation of tumor shrinkage in order to carry out breast conserving surgery, it would be better to confirm that tumor does not have PIK3CA mutations." (PMID 37106324, 2023). "Among these, the PIK3CA isoform-specific inhibitor alpelisib and the pan-AKT inhibitor capivasertib were recently approved in combination with the estrogen receptor degrader fulvestrant for the treatment of ER+ advanced breast cancer after progression on an aromatase inhibitor." (PMID 36901954, 2023). "Target prediction, bioinformatics, molecular docking, and molecular dynamics revealed that the most promising hybrid 4a may exert anti-breast cancer activity by acting on multiple targets such as EGFR, PIK3CA, and MAPK8 and thus participating in multiple tumor-related signaling pathways." (PMID 37928644, 2023).
breast cancer (continued). "LGK-974 (PORCN inhibitor) rescued enhanced proliferation of INPP4B-overexpressing PIK3CA-mutant ER+ human breast cancer cells.Pyrvinium (CK1α inhibitor) reduced viability and 3D spheroid growth of INPP4B-overexpressing PIK3CA-mutant ER+ human breast cancer cells." (PMID 37471270, 2023). "As INPP4B expression is increased in PIK3CA-mutant ER+ breast cancers where it promotes cell proliferation and tumor growth, we questioned whether INPP4B also affects the sensitivity of ER+ breast cancer cells to standard-of-care therapies." (PMID 36612130, 2022). "Furthermore, oncogenes which are often overexpressed in breast cancer such as HER2, PIK3CA, or RAS also cause senescence rather than apoptosis." (PMID 34943954, 2021). "Given the overlap between PIM and PI3K/Akt signaling and the identification of PIM kinases as mediators of resistance to PI3K and HER2 inhibition in breast cancer, we next asked whether PI3K signaling in cell lines with PIK3CA and/or HER2 alterations would compensate for PIM." (PMID 32391118, 2020). "In conclusion, our data suggest a revised model of breast cancer progression, in which IDP, especially atypical IDP lesions, can be a precursor lesion of both LG and HG carcinoma of both ductal and papillary morphology without PIK3CA mutation." (PMID 32195332, 2020). "Also, the PIK3CA E545K mutant form promotes growth of breast cancer cells by activation of SGK3, but not AKT." (PMID 30975125, 2019). "Furthermore, enforced expression of miR-126-3p in drug treatment-naive non-small cell lung cancer cells, renal cancer cells or breast cancer cells has been shown to increase sensitivity to vincristine and adriamycin, cisplatin, and CDK4/6 or PIK3CA inhibitors, respectively." (PMID 31227006, 2019). "Finally, promising disease control and survival benefits, with a manageable safety profile, have been observed with alpelisib plus fulvestrant in a Phase Ib study (NCT01219699) in patients with PIK3CA-altered estrogen receptor-positive, HER2–advanced breast cancer (ABC)." (PMID 30167089, 2018). "Our study showed that PIK3CA mutant tumors with low AKT phospho-Ser473 and high ERα phospho-Ser167 (Type G) was the most frequent type in postmenopausal women, and almost 30% of postmenopausal ER-positive, HER2-negative breast cancer were classified as this type." (PMID 29707142, 2018). "To examine the pathological and clinical features associated with cfDNA ESR1 and PIK3CA mutations in the 113 ER + /HER-cases, we looked at differences in the clinical features of the breast cancer between patients who had and did not have detectable ESR1 or PIK3CA mutations in cfDNA." (PMID 30083595, 2018). "However, as not all metastatic breast cancers are PIK3CA‐positive, additional biomarkers in the metastatic setting are needed." (PMID 29689598, 2018).